CUL3 (cullin 3)
Diseases named in the same sentence as CUL3 in open-access papers (continued):
Sharing a sentence is not in itself a finding about the gene and the disease.
breast carcinoma (13 papers, 2017 to 2025). "We, therefore, knocked down all five cullins (Cul-1, -2, -3, -4A, -4B, -5) individually, and found that only Cul-3 knockdown caused SLC7A11 accumulation in multiple breast cancer cell lines." (PMID 38959043, 2024). "Our result indicated that the depletion of CUL3 or KCTD10 caused the accumulation of RhoB protein in HER2-positive breast cancer cells." (PMID 34187934, 2021). "The upregulation of Cul3 could deplete Nrf2 in breast cancer and was associated with sensitivity to oxidative stress, carcinogens, and chemotherapy." (PMID 35242279, 2022). "For example, an early study showed that NRF2 was frequently depleted in breast cancer biopsies and breast cancer cell lines due to its augmented proteasomal degradation caused by the concomitant overexpression of the E3 ubiquitin ligase CUL3." (PMID 33805996, 2021). "However, we found support in the literature for the involvement of the selected highly central genes (COPS5, FN1, and CUL3) in breast cancer susceptibility (Sections 3.3, 3.6, and 3.8)." (PMID 33735170, 2021). "Analysis of clinical breast cancer samples revealed an inverse correlation between a high expression of CUL3/KEAP1 and IKKβ, while a combination of low KEAP1 and CUL3 expression and high IKKβ expression was a predictor of poor survival." (PMID 39941813, 2025). "In breast cancer and ovarian cancer, the E3 ligase cullin-3 (CUL3) interacts with BECN1, promoting its K48 ubiquitination and downregulating BECN1, ultimately enhancing tumor cell proliferation and resulting in a poor prognosis." (PMID 39048965, 2024). "Using siRNA to silence Cul3 in breast cancer cells, microarray analysis revealed that the expressions of oxidative stress downstream genes (AKR1C1, UGDH, TXN, GCL, and NQO1) were overexpressed at least 2-fold." (PMID 35242279, 2022). "Taken together, it is likely that the regulation of EGFR phosphorylation through PTPRH activation and RhoB degradation by the CUL3/KCTD10 E3 complex is conserved in HER2/EGFR-double positive breast cancer cells." (PMID 34187934, 2021). "For HER2/EGFR double-positive breast cancer cells, our present study suggests that RhoB functions as a tumor suppressor because its constitutive degradation by the CUL3/KCTD10 E3 complex is essential for cell proliferation of SKBR-3 cells." (PMID 34187934, 2021). "The Cullin-RING ubiquitin ligases, including CUL3, have direct links to breast cancer." (PMID 38942922, 2024). "For instance, the APP (amyloid-beta precursor protein), ESR1 (estrogen receptor 1), TUBB (beta tubulin), and CUL3 (culin-3) genes have established links to promoting cancer cell survival, adhesion, differentiation, migration, and resistance to therapy in breast cancer." (PMID 38378612, 2024). "Here, the use of siRNA against CUL3 in MCF-7 breast cancer cells increased the levels of NRF2-regulated proteins, including GCL, NQO1, AKR1C1, UGDH, TXN and the drug transporter ABCC1, ultimately conferring a resistance to the oxidants and conventional anticancer agents." (PMID 33805996, 2021). "Therefore, searching for inhibitors of CUL3 may be an important approach for treating breast cancer and ovarian cancer." (PMID 39048965, 2024). "In this study, we found that depletion of CUL3 or KCTD10 reduced the phosphorylation of EGFR and HER2, as well as cell proliferation of HER2-positive breast cancer cells." (PMID 34187934, 2021). "Here, we report that degradation of an endosomal small GTPase, RhoB, by the ubiquitin ligase complex cullin-3 (CUL3)/KCTD10 is essential for both EGFR and HER2 phosphorylation in HER2-positive breast cancer cells." (PMID 34187934, 2021). "It is likely that expression of CUL3 and KCTD10 would be reduced by microRNAs also in HER2-positive breast cancer cells under specific patho-physiological conditions." (PMID 34187934, 2021).
breast carcinoma (continued). "To examine the roles of the CUL3/KCTD10 complex in the activation of EGFR and HER2, we first examined the phosphorylation of those receptors in HER2-positive breast cancer cells." (PMID 34187934, 2021). "We previously reported that the constitutive degradation of an endosomal small GTPase RhoB by the CUL3/KCTD10 E3 complex functions in EGF-induced Rac1 activation specifically in HER2-positive breast cancer cell lines, among other breast cancer subtypes." (PMID 34187934, 2021). "Upon inhibition of miR-7641 expression, the expressions of several of the target genes (RPS16, RNF4, EMC8, and MSRB3) increased, CUL3 expression decreased, and other genes, including PIGC, remained unchanged in MCF-7 breast cancer cells." (PMID 28827731, 2017). "Additionally, the impact of CUL3 overexpression was explored in MCF-7 and MDA-MB-231 breast cancer cell lines, revealing distinct differences in molecular and phenotypic characteristics." (PMID 38942922, 2024). "Similarly, miR-7641 inhibition in MDA-MB-231 breast cancer cells upregulated RPS16, TNFSF10, MSRB3, CDNF, ZNF616, and NBEA, downregulated CUL3, and showed no remarkable changes for PIGC and the other genes." (PMID 28827731, 2017).
developmental delay (9 papers, 2021 to 2025). "As with our study, the young child with the CUL3 gene mutation suffered from development delay and speech dyspraxia." (PMID 36726778, 2023). "Till today, there are six clinical cases that have reported abnormalities resulting from CUL3 mutations, with developmental delay (DD) as the primary phenotype." (PMID 37575562, 2023). "Mutations in CUL3 or its substrate adaptor proteins have been identified in patients with congenital heart disease, developmental delay, cranio-lenticulo-sutural dysplasia, and cancers." (PMID 37626065, 2023). "For instance, heterozygous CUL3 variants have been associated with pseudohypoaldosteronism type IIIE (MIM # 614496) due to an in-frame deletion of exon 9, and only recently have loss-of-function (LoF) variants been found to be involved in overall developmental delay." (PMID 37152996, 2023). "Not all CUL3 variants cause developmental disturbances; one reported CUL3 patient, who presented with hematuria, displayed hyperkalemia and borderline blood pressure without any other growth or developmental delays." (PMID 37845702, 2023).
Gordon syndrome (9 papers, 2013 to 2025). An extremely rare multiple congenital malformation syndrome characterized by congenital contractures of hand and feet with variable degrees of severity of camptodactyly, clubfoot and, less frequently, cleft palate. "Although mutations in Kelch-like 3 and Cullin 3 are common in Gordon syndrome, finding a mutation in the MR gene, NR3C2, was unexpected." (PMID 40441250, 2025). "The phenotypic severity of Gordon syndrome varies according to different causative mutations (CUL3 > recessive KLHL3 > dominant KLHL3 > WNK4 > WNK1)." (PMID 31795491, 2019). "The DCT is highly sensitive to Gordon syndrome mutations in CUL3 because of the extremely high Kelch-like 3 expression there." (PMID 31795491, 2019). "Loss-of-function mutations in either CUL3 or KLHL3 cause the hereditary high blood pressure disease Gordon's syndrome by stabilizing WNK isoforms." (PMID 24641320, 2014). "The present study has found new mutations in the CUL3 and KLHL3genes of patients with Gordon's syndrome." (PMID 24266877, 2014). "Thus far, the E3 ubiquitin ligase cullin-3 has been linked to Gordon syndrome." (PMID 36727946, 2023). "In humans, WNK1, WNK4, CUL3, and/or KLHL3 mutations manifest as Gordon’s syndrome, a heritable form of hypertension associated with salt-sensitive hypertension, hyperkalemia, metabolic acidosis, and thiazide sensitivity." (PMID 36028759, 2022). "More recently, mutations in two further genes have been identified, KLHL3 and CUL3, which account for 80% of families with Gordon syndrome." (PMID 31795491, 2019). "A Gordon syndrome mouse model has also been created with a Klhl3 mutation in the BTB domain, which should aid a better understanding of the Kelch-like 3/Cullin 3 interaction and contribute to possible future novel antihypertensive drug targets." (PMID 31795491, 2019). "Lifton’s group, using whole exome sequencing, identified two further genes implicated in Gordon syndrome, KLHL3 (5q31), which encodes Kelch-like 3 (PHA2D), which was also identified by a French group, and CUL3 (2q36), which encodes Cullin 3 (PHA2E)." (PMID 31795491, 2019). "For instance, dopatients with KLHL3 A340V and A494T Gordon's syndrome have the same CUL3/KLHL3/WNK/SPAK/NCC pathwayabnormalities as those with KLHL3 L387P?" (PMID 24266877, 2014). "Since the recognition of this predominantly autosomal dominant condition in the 1960s, the study of families with Gordon syndrome has revealed four genes WNK1, WNK4, KLHL3, and CUL3 to be implicated in its pathogenesis after a phenotype–genotype correlation was realised." (PMID 31795491, 2019). "The identification of mutations in CUL3 and KLHL3 in Gordon's syndrome patients suggeststhat these two proteins may also form a CRL E3 complex that regulates blood pressure." (PMID 23387299, 2013). "We next selected 15 different dominant Gordon's syndrome mutations located in different domainsof KLHL3, generated in stable HEK-293 cell lines,and tested how each mutation affects association with CUL3 and WNK1." (PMID 23387299, 2013). "Another example is Gordon syndrome (also known as pseudohypoaldosteronism type II or familial hyperkalemic hypertension syndrome), in which a loss-of-function mutation in cullin-3 affects proteasomal degradation of the with-no-lysine (WNK) serine-threonine kinase family (WNK1 and WNK4)." (PMID 36727946, 2023). "CUL3 knock-out models show significant defects along all nephron segments and also resulted in reductions on other tubular proteins, such as AQP2 and NKCC2, which override increased NCC expression, so a phenotype of salt wasting and polyuria develops rather than Gordon syndrome." (PMID 31795491, 2019).
melanoma (8 papers, 2014 to 2024). A malignant, usually aggressive tumor composed of atypical, neoplastic melanocytes. "Using a forward genetic screen, we identified loss of NF1 and CUL3 as drivers of vemurafenib resistance in melanoma, independently confirming results from similar genetic screens." (PMID 32346533, 2020). "While our results indicate that the loss of CUL3 leads to the activation of RAC1 in melanoma cells and confers resistance to BRAFi, the exact mechanism leading to RAC1 activation in CUL3KD cells is still unclear." (PMID 32346533, 2020). "How the loss of CUL3 contributes to BRAFi resistance in melanoma is less clear." (PMID 32346533, 2020). "Previous CRISPR screen of CREs on melanoma cells has been performed on several critical genes, including NF1, NF2, and CUL3, whose loss-of-function mutations resulted in vemurafenib resistance." (PMID 37904237, 2023). "A high-resolution CRISPR screen of non-coding functional elements surrounding three genes, including NF1, NF2, and CUL3, uncovered several critical CREs that modulate drug resistance in melanoma." (PMID 37904237, 2023). "We also performed the knockdown of CUL3 in a second melanoma cell line, 451.Lu." (PMID 32346533, 2020). "Loss of either CUL3, FBXL6, or RBX1 expression conferred a growth advantage in the presence of vemurafenib, indicating that an unimpaired SCF complex is critical for vemurafenib sensitivity in melanoma." (PMID 29880484, 2018). "In this context, as PI3K activity is activated in a broad spectrum of cancer types, it would be interesting to identify late endosomal modulators (i.e. Cul3) that may compensate for low RAB7 levels in these non-melanoma cellular lineages." (PMID 26008978, 2015). "The data showed that in melanoma cells with stable knockdown of BRCA1, CUL3, RNF4, UBR5, and CHIP, the reduction in CIP2A levels upon PF treatment was not reversed." (PMID 39399646, 2024). "Among them, six E3 ligases were highly expressed in melanoma cells: BRCA1, CUL3, RNF4, UBR5, CHIP, and von Hippel‒Lindau (VHL)." (PMID 39399646, 2024). "The lentivirus-encapsulated GeCKO library was transfected into melanoma cells, and new melanoma resistance-related genes NF2, CUL3, TADA2B, and TADA1 were identified by vemurafenib resistance screening." (PMID 37834313, 2023). "A CRISPR-Cas9 knock-out screening identified additional candidate genes whose ablation conferred resistance to BRAF inhibitor in melanoma cell line, including neurofibromin 2 (NF2), Cullin 3 E3 ligase (CUL3), and members of the STAGA histone acetyltransferase complex (TADA1 and TADA2B)." (PMID 24743024, 2014).
lung adenocarcinoma (7 papers, 2014 to 2024). A carcinoma that arises from the lung and is characterized by the presence of malignant glandular epithelial cells. "More research needs to be done to figure out the underlying molecular mechanism of mutations of the KEAP1/NFE2L2/CUL3 pathway in lung adenocarcinoma, and there is still a long way to go to target these mutations as a new therapeutic strategy." (PMID 34617407, 2021). "It is imperative to mine the underlying mechanisms and characteristics of KEAP1/NFE2L2/CUL3 mutations in lung adenocarcinoma and accelerate the investigations of the pathway and the targeted drugs." (PMID 34617407, 2021). "CUL3, encoding the ubiquitin ligase adaptor that binds to Keap1 and degrades Nrf2, was also associated with radiation resistance in adenocarcinoma of the lung." (PMID 27109210, 2016). "Therefore, our further research needs more samples to provide a more accurate subgroup analysis of KEAP1/NFE2L2/CUL3 pathway mutations so as to exhibit a deeper insight into KEAP1/NFE2L2/CUL3 pathway mutation in lung adenocarcinoma progression." (PMID 34617407, 2021). "Generally, our study comprehensively analyzed the multiplatform data of TCGA to compare the biologic characteristics, intrinsic heterogeneities, and clinical features of the KEAP1/NFE2L2/CUL3 mutant and wild lung adenocarcinoma patients." (PMID 34617407, 2021). "KEAP1 mutations, which typically decrease ubiquitylation and turnover of Nrf2, are found in 16.8% (154/915) of recent lung adenocarcinoma samples (MSK-IMPACT), while CUL3 mutations are infrequent at 1.5% (14/915)." (PMID 31581742, 2019). "Since KEAP1/NFE2L2/CUL3 gene mutations have not received enough attention in the clinical practice of lung adenocarcinoma, these three genes are not included in routine postoperative pathologic sample gene mutation detection in our hospital." (PMID 34617407, 2021). "Indeed, we found that although in the TCGA lung adenocarcinoma data, the cumulative alteration frequency of NRF2, KEAP1, and CUL3 is 23%, 58% of patients within our lung adenocarcinoma cohort had high levels of NRF2 protein." (PMID 31455821, 2019). "We identified alterations in genes involved in chromatin remodeling (PBRM1, SETD2), oxidative stress (CUL3, SOD2), immune response (CSMD3, SYK), and gamma-aminobutyric acid receptor signaling (GABRD, GABRG1) in lung adenocarcinoma." (PMID 24576404, 2014).
ovarian carcinoma (7 papers, 2014 to 2024). A malignant neoplasm originating from the surface ovarian epithelium. "Cell viability assays, carried out in the presence of 5 μM cisplatin, confirmed a potentiation of cisplatin toxicity upon down regulation of CUL3 for SKOV3 and ES2 ovarian carcinoma cells." (PMID 31690264, 2019). "It has been shown that underexpression of RBX1, due to gene CNL, might interfere with the KEAP1/CUL3/RBX1 complex, which also displays a E3 ubiquitin-ligase activity in thyroid and ovarian cancer." (PMID 25298778, 2014). "While the magnitude and frequency of KEAP1/CUL3/RBX1 complex component disruption were more prominent in the cohort we assessed, these results reveal the potential importance of alternative mechanisms of NRF2 activation in ovarian cancer and warrant consideration in future studies." (PMID 25114896, 2014).
liver cancer (6 papers, 2016 to 2025). An epithelial or non-epithelial malignant neoplasm that arises from the liver. "Cul3 loss expression has been detected in a wide range of human liver cancers and correlated directly with tumor de‐differentiation." (PMID 27401257, 2016). "CUL3 is an E3 ligase which is strongly involved in DNA synthesis and the formation of micronuclei, and loss of CUL3 in hepatocytes can result in upregulation of cyclin E although this phenomenon is also showed in a large series of human liver cancers." (PMID 32555680, 2020). "Our study confirmed that loss of function of Cul3 alone failed to induce liver cancer." (PMID 34803491, 2021).
lung squamous cell carcinoma (6 papers, 2012 to 2020). "A very recent comprehensive genomic characterisation study on squamous cell lung cancer conducted by the Cancer Genome Atlas Research Network reported the occurrence of mutations in NRF2, KEAP1, or CUL3 in 34% of 178 lung squamous cell carcinomas." (PMID 24278719, 2012). "The frequency of disruption for ovarian tumors was comparable to the high frequencies observed in uterine carcinoma and lung squamous cell carcinoma (LUSC), where disruption of the KEAP1/CUL3/RBX1 E3-ubiquitin ligase complex is well established." (PMID 25114896, 2014).
prostate carcinoma (6 papers, 2009 to 2025). A carcinoma that arises from epithelial cells of the prostate gland. "Studies have shown that ERK1/2 inhibits the Cullin 3/SPOP-mediated ubiquitination and degradation of PrLZ, regulating prostate cancer progression." (PMID 40764425, 2025). "In this study, we demonstrated that SPOP forms a functional CUL3-SPOP-RBX1 E3 ubiquitin ligase complex that targets ATF2 for ubiquitination and proteasomal degradation in prostate cancer cells, contributing to facilitating prostate cancer cell migration and invasion." (PMID 29996942, 2018). "In particular, CUL3, over expressed in kidney and prostate cancers, is a target of several dysregulated MIRs: MIR22, MIR23A, MIR23B, MIR218-1, MIR218-2, and MIR301, which are down regulated in kidney cancers, and of MIR22, MIR23A, MIR181A, and MIR181C, which are down regulated in prostate cancers." (PMID 19402918, 2009).
schizophrenia (6 papers, 2020 to 2025). A major psychotic disorder characterized by abnormalities in the perception or expression of reality. "We illustrate multiple isoTWAS associations undetectable at the gene-level, prioritizing isoforms of AKT3, CUL3 and HSPD1 in schizophrenia and PCLO with multiple disorders." (PMID 38036788, 2023).